TJP3 (tight junction protein 3)
Description:
TJP1, TJP2, and TJP3 are closely related scaffolding proteins that link tight junction (TJ) transmembrane proteins such as claudins, junctional adhesion molecules, and occludin to the actin cytoskeleton. The tight junction acts to limit movement of substances through the paracellular space and as a boundary between the compositionally distinct apical and basolateral plasma membrane domains of epithelial and endothelial cells. Binds and recruits PATJ to tight junctions where it connects and stabilizes apical and lateral components of tight junctions. Promotes cell-cycle progression through the sequestration of cyclin D1 (CCND1) at tight junctions during mitosis which prevents CCND1 degradation during M-phase and enables S-phase transition. With TJP1 and TJP2, participates in the junctional retention and stability of the transcription factor DBPA, but is not involved in its shuttling to the nucleus (By similarity). Contrary to TJP2, TJP3 is dispensable for individual viability, embryonic development, epithelial differentiation, and the establishment of TJs, at least in the laboratory environment (By similarity).
Synonyms: ZO3; ZO-3
Tractability: Antibody: UniProt places it where antibodies can reach, with high confidence; its Gene Ontology location is reachable by antibodies, with high confidence. PROTAC: ubiquitination databases record sites on it; its protein half-life has been measured.
Gene: Protein-coding gene on chromosome 19 (3,708,356 to 3,750,813, forward strand). Ensembl gene ENSG00000105289.
Subcellular location: Cell membrane; Cell junction, tight junction; Nucleus
Subcellular location (Human Protein Atlas): Cell Junctions; Nucleoplasm; Plasma membrane
Gene Ontology:
Molecular function: protein binding; cell adhesion molecule binding
Biological process: cell-cell adhesion; cell-cell junction organization; establishment of endothelial intestinal barrier; maintenance of blood-brain barrier; positive regulation of blood-brain barrier permeability; protein localization to cell-cell junction
Cellular component: bicellular tight junction; cell junction; nucleoplasm; nucleus; plasma membrane; cell-cell junction; tight junction
Genetic constraint (gnomAD): Loss-of-function variants: 85 observed, 95.99 expected, observed/expected ratio (o/e) 0.89, 90% interval 0.74 to 1.06. The upper end of that interval is the gene's LOEUF score, 1.06, which puts it in group 4 of 6, group 1 being the genes least tolerant of losing a copy. Missense variants: 1,331 observed, 1,257.1 expected, observed/expected ratio (o/e) 1.06, 90% interval 1.01 to 1.11. Synonymous variants: 542 observed, 516.52 expected, observed/expected ratio (o/e) 1.05, 90% interval 0.98 to 1.13.
Homologues: Orthologues: chimpanzee TJP3 (99% identical), macaque TJP3 (95% identical), pig TJP3 (85% identical), dog TJP3 (84% identical), rat Tjp3 (80% identical), mouse Tjp3 (80% identical), tropical clawed frog tjp3 (57% identical), zebrafish tjp3 (49% identical), Drosophila melanogaster pyd (31% identical), Caenorhabditis elegans zoo-1 (28% identical). Paralogues in human: TJP1 (44% identical), TJP2 (42% identical), DLG5 (21% identical).
Diseases named in the same sentence as TJP3 in open-access papers:
TJP3 is named in the same sentence as 27 diseases in open-access papers, as found by Europe PMC text mining. Sharing a sentence is not in itself a finding about the gene and the disease. The quoted sentences say what the papers report.
breast carcinoma (8 papers, 2010 to 2024). "TJP3 promotes chemoresistance, tumor metastasis and potential immunotherapy escape in breast cancer." (PMID 37950731, 2023). "It ranks the importance of hub-gene in ARG subgroups identification, and the top3 genes are SFN, TJP3 and TACSTD2, amongst while only TJP3 (HR = 1.95, p = 1.3e-8) is prognosis-related gene in breast cancer." (PMID 37950731, 2023). "Meantime, Alive&dead assay is performed, and the results show that down-regulation of TJP3 enhances the toxicity of GEM in breast cancer cells (p < 0.05)." (PMID 37950731, 2023). "TJP3 functions in maintaining tight junction integrity and in transducing regulatory signaling events in patients with primary breast cancer." (PMID 20830311, 2010).
ovarian carcinoma (4 papers, 2022 to 2024). A malignant neoplasm originating from the surface ovarian epithelium. "NEAT1 can upregulate the expression of TJP3, MEST, and ROCK1 in ovarian cancer cell lines, subsequently promoting the progression of ovarian cancer." (PMID 36011001, 2022). "TJP3 is reported to participate in drug tolerance in long non-coding RNA NEAT1-mediaed tumor invasion in ovarian cancer, and it is involved in treatment sensitivity of FPDHP in human cancer cells." (PMID 37950731, 2023). "Multiple putative miRNA targets of NEAT1 and the downstream proteins have been proposed to contribute to the oncogenic roles of NEAT1 in ovarian cancer, such as the NEAT1/miR-1312/TJP3, NEAT1/miR-506, NEAT1/let-7 g/MEST/ATGL, NEAT1/miR‐382‐3p/ROCK1, and NEAT1/miR-365/FGF9 axes." (PMID 37986114, 2023).
asthma (2 papers, 2022 to 2024). "TJP3 and CLDN8, which contribute to formation of tight junctions and their permeability, had decreased expression which supported the development of the asthma-like phenotype." (PMID 38706568, 2024).
lung carcinoma (2 papers, 2021 to 2023). "Three genes, P4HA2, TJP3, and BAIAP2L1, have been shown to be associated with lung cancer B lymphocytes in situ." (PMID 34575089, 2021). "As for TJP3, although no direct evidence has connected such a gene with lung cancer B cells, it has been reported to participate in the regulation of antibody-mediated immune responses during lung tumorigenesis, validating such a result." (PMID 34575089, 2021).
bladder cancer (1 paper, 2022). "In this study, we investigated whether the ZO family (TJP ZO1, ZO-2, and ZO-3, encoded by the TJP1, TJP2, and TJP3 genes, respectively) is associated with the malignant phenotype in bladder cancer." (PMID 35087173, 2022). "We found TJP2 expression was positively correlated with IC50 of cisplatin, and TJP3 expression was positively correlated with IC50 of mitomycin C in bladder cancer cell lines." (PMID 35087173, 2022). "We also found TJP2 and TJP3 mRNA expression positively correlated with chemoresistance in bladder cancer cell lines." (PMID 35087173, 2022). "TJP1 and TJP3 had a 2.5–4% amplification ratio and TJP2 has a 5% mutation ratio in bladder cancer patients." (PMID 35087173, 2022). "The genetic alterations of the TJP family in bladder cancer, examined using cBioPortal, showed that the genetically altered ratios of TJP1, TJP2, and TJP3 were 3%, 3%, and 1.7%, respectively." (PMID 35087173, 2022).
endometrial cancer (1 paper, 2022). Primary or metastatic malignant neoplasm involving the endometrium (mucous membrane that lines the endometrial cavity). "Specifically, we have confirmed the role of deregulated CLDN and OCLN genes (which encode integral membrane proteins) and provided strong additional evidence for deregulated F11R (JAM-A) and TJP3 (ZO-3) in the development of endometrial cancer." (PMID 36484008, 2022). "Further, we observed overexpression of an additional three genes in 8 of the 9 endometrial cancer cell lines: OCLN (occludin), F11R (JAM-A) and TJP3 (ZO-3)." (PMID 36484008, 2022).
fatty liver disease (1 paper, 2023). A reversible condition wherein large vacuoles of triglyceride fat accumulate in liver cells via the process of steatosis. "TJP3 encodes a tight junction transmembrane protein that controls lipid diffusion and its slight dysfunction has been implicated in fatty liver disease." (PMID 37859957, 2023).
lung adenocarcinoma (1 paper, 2019). A carcinoma that arises from the lung and is characterized by the presence of malignant glandular epithelial cells. "In addition, factors previously identified to be specific markers of lung adenocarcinoma were upregulated, including PROM2, CLDN3, and TJP3, as were genes proposed to have potential diagnostic or prognostic value in human cancers, including MMP9, AGR2, SULF1, NHSL1, LGR5, MUC1, and PIK3C2G." (PMID 31434729, 2019).
cancer (13 papers, 2019 to 2024). A tumor composed of atypical neoplastic, often pleomorphic cells that invade other tissues. "Next, by examining the DNA copy numbers of the TJP family in multiple cancer cell lines, we observed that the DNA copy numbers of TJP1, TJP2, and TJP3 were upregulated in 10, 9, and 7 different cancer cell lines, respectively." (PMID 35087173, 2022). "Moreover, nuclear-enriched abundant transcript 1 (NEAT1) was found to sponge miR-1321 and thus regulate the expression of the tight junction protein 3 (TJP3) (an important factor in cancer development), resulting in EMT promotion, invasion, and migration of OC cells." (PMID 37373222, 2023). "By evaluating the mRNA expression of TJP1, TJP2, and TJP3 in 40 different cancer cell lines, we found that TJP1, TJP2, and TJP3 were upregulated in 29, 40, and 12 different cancer cell types, respectively." (PMID 35087173, 2022). "As a result, three genes, SH3BGRL2, TJP3 and TRIM31, were positively correlated with TMPRSS2 and TMPRSS4 for all cancer cell lines and showed distinct differential expression profiles across GI solid tumors." (PMID 35970857, 2022). "Investigating the proteins driving cluster 1, we found lower levels of circulating proteins regulating DNA repair/integrity (RBBP8, RAD21) and cell fate/replication (NOTCH3, TJP3, HNRNPA2), which play a role in cancer development." (PMID 35033985, 2022). "As a general feature, the expression of epithelial genes (e.g. TJP3, TSPAN13, CLDN7 and EPCAM) was positively correlated with the expression of AGR2/3 and the expression of mesenchymal genes (e.g. VIM and MSN) was negatively correlated, with specific correlations according to cancer type." (PMID 35857928, 2022). "Also, HOPX was correlated with genes in a manner toward suppression of cancer cell progression; downregulation of TNRC6C, PAX8, TSHR, DYRK1A/B, and SLIT3 (pro-proliferation/migration), and upregulation of PCDH8/9, CDC42EP3/4/5, and TJP3 (anti-proliferation/migration)." (PMID 31666923, 2019).
tumor (5 papers, 2019 to 2024). "Furthermore, we found that the gene encoding the tight junction protein 3 (Claudin3/CLDN3) is specifically expressed in tumor stem cells." (PMID 38534739, 2024). "Their trend of expression showed most of them to be upregulated in the tumor samples, regardless of the disease stage, while only PPL, ALDH1A1, GSTA1, TJP3 and CRYAB were downregulated in HNSCC." (PMID 37686696, 2023).
infection (2 papers, 2022). The state of being infected such as from the introduction of a foreign agent such as serum, vaccine, antigenic substance or organism. "Recently, Han Zhao and colleagues identified that, after infecting Vero-E6 cells, PEDV downregulates expression of miRNA-328-3p and the resulting reduced inhibition of the target tight junction protein 3 (TJP-3/ZO-3) helps to enhance PEDV infection." (PMID 35458536, 2022).
TJP3 also shares sentences with these, for which no sentence is quoted: colitis (2 papers); Sepsis (2); adenocarcinoma (1); alcoholic fatty liver (1); allergies (1); brain tumors (1); breast invasive carcinoma (1); colon cancer (1); colorectal adenocarcinoma (1); conjunctivitis (1); obstructive sleep apnea (1); otitis media (1); pharyngitis (1); sinusitis (1); staphylococcus aureus infection (1); viral infection (1).